ZNF578 (zinc finger protein 578)
Description:
May be involved in transcriptional regulation.
Synonyms: FLJ31384
Tractability: PROTAC: ubiquitination databases record sites on it.
Gene: Protein-coding gene on chromosome 19 (52,453,553 to 52,516,882, forward strand). Ensembl gene ENSG00000258405.
Subcellular location: Nucleus
Gene Ontology:
Molecular function: protein binding; DNA-binding transcription factor activity, RNA polymerase II-specific; RNA polymerase II cis-regulatory region sequence-specific DNA binding
Biological process: regulation of transcription by RNA polymerase II; regulation of DNA-templated transcription
Cellular component: nucleus
Genetic constraint (gnomAD): Loss-of-function variants: 8 observed, 8.6 expected, observed/expected ratio (o/e) 0.93, 90% interval 0.54 to 1.63. That is too few expected variants to judge how well the gene tolerates losing a copy. Missense variants: 726 observed, 727.41 expected, observed/expected ratio (o/e) 1, 90% interval 0.94 to 1.06. Synonymous variants: 206 observed, 237.05 expected, observed/expected ratio (o/e) 0.87, 90% interval 0.77 to 0.98.
Homologues: Orthologues: chimpanzee ZNF578 (94% identical). Paralogues in human: ZNF813 (70% identical), ZNF888 (68% identical), ZNF860 (67% identical), ZNF816 (67% identical), ZNF761 (66% identical), ZNF765 (64% identical), ZNF468 (61% identical), ZNF525 (57% identical), ZNF701 (55% identical), ZNF766 (40% identical).
Diseases named in the same sentence as ZNF578 in open-access papers:
ZNF578 is named in the same sentence as 1 disease in open-access papers, as found by Europe PMC text mining. Sharing a sentence is not in itself a finding about the gene and the disease.
ZNF578 shares sentences with these, for which no sentence is quoted: tumor (1 paper).